BRCA1 (BRCA1 DNA repair associated)
Diseases named in the same sentence as BRCA1 in open-access papers (continued):
Sharing a sentence is not in itself a finding about the gene and the disease.
ovarian carcinoma (continued). "Of note, this behavior was also confirmed using the 29 BRCA1/2 mutated TCGA ovarian cancer samples (data not shown)." (PMID 40427638, 2025). "Germ-line genetic testing for a panel of cancer-susceptibility genes is recommended in all epithelial ovarian cancer cases, but it is not always available in clinical practice, and, in some cases, it is limited to BRCA1/2." (PMID 39984762, 2025). "Germline pathogenic variants in BRCA1 and BRCA2 confer high risks of breast and ovarian cancer." (PMID 40399999, 2025). "The aim of the current study is to determine whether Dutch women proven to be BRCA1/2 GPV carriers have an increased risk of malignancies other than breast and ovarian cancer at an early age." (PMID 40427184, 2025). "Overall, in breast and ovarian cancer screening programs for women in China, incorporating BRCA1/2 genetic testing for individuals with a family history, along with appropriate preventive measures for those who test positive, increases the population’s QALY by 0.26 days." (PMID 40567951, 2025). "Additionally, BAs can influence the expression and activity of various PARP enzymes, and deoxycholic acid can regulate the expression of BRCA1 and estrogen receptors, thereby controlling the drug sensitivity of ovarian cancer cells." (PMID 40535134, 2025). "Pathogenic variants in the BRCA1 and BRCA2 genes, belonging to the category of DNA double-strand-break repair genes, place female carriers at risk of developing several malignancies, of which breast or ovarian cancers are the most significant." (PMID 41002733, 2025). "These trials demonstrated that PARPi (olaparib, niraparib, rucaparib) significantly improved PFS in patients with high-grade ovarian cancer, both with and without BRCA1/2 mutations, compared to placebo." (PMID 40382284, 2025). "Finally, the assessment of silencing states to make treatment decisions is already here, as ovarian cancer patients with silenced BRCA1/2 now have more treatment options." (PMID 41315265, 2025). "The approval of niraparib for the treatment of ovarian cancer without BRCA1/2 mutations suggests a potential efficacy of PARPi in other BRCA wild‐type cancers." (PMID 39778077, 2025). "Thus, the current recommendation for women with BRCA1 and BRCA2 mutations is to consider bilateral salpingo-oophorectomy (removal of both ovaries and fallopian tubes) to reduce the risk of developing ovarian cancer." (PMID 41154374, 2025). "A synergistic enhancement in pRPA32 phosphorylation in replicating cells (EdU+ cells) upon treatment with DHS and talazoparib was even observed in lower concentration of DHS in SK‐OV‐3 cells and other BRCA1/2 wild‐type ovarian cancer cell lines PA‐1, OAW42 and A2780." (PMID 40089867, 2025). "It is widely recognized in the field of synthetic lethality that molecularly targeted therapies such as PARP inhibitors possess the potential to greatly extend the progression-free and overall survival rates for individuals with BRCA1- or BRCA2-mutant ovarian cancer." (PMID 40781291, 2025). "In previous studies, the synergetic effect of olaparib, a PARP inhibitor, combined with CDKI-73, a CDK9 inhibitor, was reported in BRCA1-proficient ovarian cancer cells; the combination resulted in a reduction of BRCA1 expression and recruitment to DNA damage sites." (PMID 40713627, 2025). "BRCA1 and BRCA2 mutations associated with breast and ovarian cancers." (PMID 41180630, 2025). "BRCA1 and BRCA2 are tumor suppressor genes located on chromosomes 17q21 and 13q12, respectively, which are responsible for an increased risk of developing breast and ovarian cancer." (PMID 40429755, 2025).
ovarian carcinoma (continued). "Decades of research have shown that mutations in BRCA1, BRCA2, and other genes involved in homologous recombination (HR) are significant prognostic indicators for survival and response to platinum-based therapy in ovarian cancer." (PMID 40076854, 2025). "The most critical non-modifiable risk factors for ovarian cancer are germline mutations in BRCA1 and BRCA2." (PMID 41008855, 2025). "In the test cohort, Chr3(q26.2) Amp was enriched in ovarian cancer with BRCA1/2 mutations compared with those without (P < 0.001)." (PMID 40687614, 2025). "One of the first biomarkers identified in ovarian cancer treatment was BRCA1/2." (PMID 40507303, 2025). "Similarly, in the PRIMA trial, niraparib significantly improved survival outcomes in patients with homologous recombination deficiency (HRD), including those with BRCA1 or BRCA2 mutations, in newly diagnosed advanced ovarian cancer at high risk of recurrence." (PMID 40075604, 2025). "There is no data yet on how this group of drugs will change the landscape in the case of ovarian cancer without BRCA1/2 mutations, but based on the results of clinical trials, it is assumed that patients will live much longer." (PMID 40429755, 2025). "Pathogenic variants in BRCA1 and BRCA2 and several other genes are risk factors for ovarian cancer, conferring a 17–44% lifetime risk of ovarian cancer for females with pathogenic variants in the BRCA1 or BRCA2 genes, as well as increased risks for breast (72%) and other cancers." (PMID 40227675, 2025). "However, in ovarian cancer, germline alterations (20.0%) exceeded somatic ones (15.2%), with BRCA1/2 germline alterations at 15.4%." (PMID 40420266, 2025). "The same kinetics of ssDNA gap repair were also observed using the BRCA1 exon 11 mutant ovarian cancer cell line UWB1.289 (referred to here as UW) and its complemented derivative expressing wild-type BRCA1 (UW + BRCA1), confirming that the observed phenotype is not cell type-specific." (PMID 40127955, 2025). "Interestingly, in ovarian cancer, BRCA1/2 biallelic alterations were primarily due to gene LOH with germline or somatic alteration, while dual somatic or combinations alterations were rare." (PMID 40420266, 2025). "BRCA1 and/or BRCA2 mutations (BRCAm) are established mechanisms of homologous recombination deficiencies (HRDs) known to play a role in ovarian cancer and may be germline (g) or somatic (s) in origin." (PMID 40097725, 2025). "BRCA1/2 mutations are associated with highly elevated but still not fatal risk of breast and ovarian cancer." (PMID 41374957, 2025). "In particular, risk factors are common and include age, family history of ovarian cancer, family history of breast cancer, a personal history of breast or ovarian cancer, BRCA1 or BRCA2 mutation, never having given birth, and estrogen hormone therapy." (PMID 41357196, 2025). "In the pan-cancer cohort (TCGA-PANCAN*) and the in-house ovarian cancer cohort, the level of fdeam was not significantly different between monoallelic BRCA1/2-mutated tumors and tumor without alteration in the HR pathway." (PMID 40730886, 2025). "Few studies on Colombian breast/ovarian cancer cases have reported a yield of PVs of 11% to 22% on selected cases based on international criteria and using multigene cancer panels (25 to 143 genes), with BRCA1/2 genes contributions between 7.2% to 17.6%." (PMID 40065011, 2025). "This paradoxical role suggests that targeting both STING-induced VEGF-A production and boosting immune cell infiltration could improve therapies for BRCA1-mutant ovarian cancers." (PMID 39949780, 2025). "However, half of the identified pathogenic HDR gene variants in EC patients were in BRCA1 or BRCA2, which calls for counseling in regard of breast and ovarian cancer risk in some 2% of EC patients and their family members from Kazakhstan." (PMID 39400928, 2025).
ovarian carcinoma (continued). "Currently PARP inhibitors have been approved apart for ovarian cancer also for breast and pancreatic cancer patients harboring germline BRCA1/2 alterations as well as in prostate cancer patients with BRCA1/2 and other HR gene alterations, both germline and somatic." (PMID 41465396, 2025). "The ovarian cancer incidence by age 70 is 44%–59% in BRCA1 carriers and 17%–35% in BRCA2 carriers." (PMID 39907309, 2025). "Conversely, most hereditary ovarian cancer cases are attributed to BRCA1/2 genes." (PMID 40076468, 2025). "The authors proposed a compensatory mechanism for maintaining SIRT1-related functions that could provide therapeutic options for BRCA1-related ovarian cancers in the context of ER stress resistance." (PMID 40429877, 2025). "A similar study conducted in a Chinese cohort with familial breast and/or ovarian cancer that lacked BRCA1/2 mutations observed a deleterious variant (c.339G>A, W113X) in FANCC." (PMID 41296379, 2025). "In our work, we aimed to identify proteins specifically upregulated in mutated BRCA1 and BRCA2 breast and ovarian cancers that could be used as targets for the development of novel therapies." (PMID 40647506, 2025). "For example, genomic biomarkers such as EGFR and BRCA1/2 mutations guide targeted therapies like EGFR inhibitors (erlotinib, gefitinib) for NSCLC and PARP inhibitors (olaparib, niraparib) for BRCA1/2‐mutated breast and ovarian cancers." (PMID 40636286, 2025). "Moreover, in our previous study of BRCA1 epimutations in ovarian cancer patients, we observed an age-related drop in methylation frequency among patients as well as controls." (PMID 40225940, 2024). "This has been demonstrated in ovarian cancer cells lines with BRCA1 mutations although 53BP1 does not mediate resistance in BRCA2 mutated cells." (PMID 39135999, 2024). "BRCA1 and BRCA2 genes play a critical role in DNA repair, and individuals who inherit pathogenic variants (PVs) in these genes face a substantially increased risk of developing breast and ovarian cancers." (PMID 39767183, 2024). "In addition, a phase II study also showed that the combination of Cediranib and Olaparib significantly improved the overall survival of patients with BRCA1/2 wild-type ovarian cancer (37." (PMID 39156700, 2024). "The BRCA1 c.843_846delCTCA has been reported in the Romanian population, with the following two cases identified: one in a patient with BC and one in a patient with ovarian cancer." (PMID 39796670, 2024). "Based on these observations, one might suggest that BRCA1 promoter methylation might be used as a prognostic biomarker to recognize breast or ovarian cancer patients who might benefit from cisplatin treatment." (PMID 38256203, 2024). "However, we show that UBC13 inhibition sensitizes BRCA1-deficent UW ovarian cancer cells to replication stress induction by HU to a greater extent than in BRCA1-proficient UW + B1 controls." (PMID 38943334, 2024). "However, only 30% of ovarian cancer patients have BRCA1/2 mutations, and fewer than 50% of patients with HRD also have BRCA1/2 mutations." (PMID 39247812, 2024). "In this trial, no increase in ovarian cancer risk for BRCA1/2-pV carriers was observed following HRT (OR 0.93; 95% CI 0.56–1.56)." (PMID 39259360, 2024). "Approximately 80% of BRCA1/2 positive breast and ovarian cancers are diagnosed at stages II-IV." (PMID 39529133, 2024). "In addition, based on recent studies, maintenance therapy with PARP inhibitors, depending on the tumor molecular analysis (including BRCA1/2 mutations and HRD status), is recommended for all patients with advanced ovarian cancer." (PMID 39518021, 2024).
ovarian carcinoma (continued). "Does hormone replacement therapy (HRT) influence breast and ovarian cancer risk of non-diseased BRCA1/2-pV carriers without risk-reducing salpingo-oophorectomy (RRSO)?" (PMID 39259360, 2024). "Additionally, mutations in BRCA1 and BRCA2 are linked to heightened risks of breast and ovarian cancers." (PMID 39391434, 2024). "Our findings suggest that CHIR-124 could offer similar benefits in both BRCA1-mutant and wild-type breast and ovarian cancers when combined with PARPi." (PMID 38993666, 2024). "PARP inhibitors exploit synthetic lethality in BRCA1/2 mutant ovarian cancer." (PMID 38391958, 2024). "Previous results regarding women from the same geographical area affected by breast and/or ovarian cancers showed a relatively lower frequency rate of BRCA1/2 PVs (14.8%, 200 out of 1346 probands) compared to males with BC investigated in our study (17%, 17 out of 100 probands)." (PMID 38974244, 2024). "Additionally, the role of BRCA1 in suppressing ER-α signaling, especially in ovarian cancer cells, underscores its tissue-specific effect." (PMID 38543119, 2024). "Epigenetic inactivation of BRCA1 has mainly been observed in breast and ovarian carcinomas." (PMID 38256203, 2024). "The BRCA1 and BRCA2 genes were discovered via research on breast–ovarian cancer predisposition." (PMID 38612902, 2024). "Interestingly, BRCA1 promoter hypermethylation was observed in melanoma and head and neck cancer, in addition to breast and ovarian cancers, where it has been typically described." (PMID 39406235, 2024). "Does the use of hormonal contraceptives influence breast or ovarian cancer risk of non-diseased BRCA1/2-pV carriers?" (PMID 39259360, 2024). "In breast and ovarian cancer, the first case–control study predicting BC in women without any pathogenic variants in BRCA1/2 genes developed an SNP18 PRS with an OR of 1.55 (95% CI 1.29 to 1.87) and an AUC of 0.59, demonstrating the PRS feasibility." (PMID 38397209, 2024). "Germline mutations in BRCA1 and BRCA2 genes are among the main causes of hereditary ovarian cancer." (PMID 38641594, 2024). "Historically, BRCA1/2 testing was biased towards patients with a family history of breast/ovarian cancer and focused on patients with early-onset disease, which may explain higher mutation detection rates in other studies." (PMID 38519644, 2024). "In the presence of heterozygous BRCA1 pathogenic variants (PV), but without associated clinical signs of FA, and in the absence of a familial history of breast or ovarian cancers, an assessment of the actual oncological risk in this patient is difficult." (PMID 39596525, 2024). "Additionally, single-gene methylation biomarkers such as RASSF1A and BRCA1 are significant factors in the onset and progression of ovarian cancer." (PMID 39345884, 2024). "Overall, data on the association between HRT and breast or ovarian cancer risk in BRCA1/2-pV carriers without RRSO is limited." (PMID 39259360, 2024). "Therefore, the study aimed to investigate the prevalence of germline mutations in BRCA1 and BRCA2 in women with ovarian cancer treated in the Public Health System in Pernambuco, Brazil." (PMID 38641594, 2024). "As ovarian cancer is still the most lethal gynecological cancer and is mainly diagnosed in its advanced stages, timely risk-reducing bilateral salpingoophorectomy (RRBSO) is recommended for BRCA1/2 mutation carriers." (PMID 38892081, 2024). "In addition to BRCA1/2, secondary mutations in other HRR genes, like RAD51C and RAD51D, play a role in restoring a functional HRR pathway in ovarian cancer." (PMID 38396858, 2024).
ovarian carcinoma (continued). "If confirmed, this association suggests that controlling blood molybdenum level through diet might reduce the risks of ovarian cancer in BRCA1 positive women." (PMID 39300540, 2024). "Of 78 ovarian cancer patients with germline P/LP variants, 40 had BRCA1, 17 had BRCA2, and 22 had non-BRCA variants." (PMID 38355628, 2024). "Patients with this subtype of ovarian cancer who are negative for somatic mutations of the BRCA1 and BRCA2 genes will be subsequently tested for HRD (Homologous Recombination Deficiency) score evaluation." (PMID 38785549, 2024). "The mutations in BRCA1 and BRCA2 increase the risk of developing breast and ovarian cancers." (PMID 39456709, 2024). "The use of gene panels searching for mutations in HR-related genes other than BRCA1/2 failed to predict response to PARPi in ovarian cancers, limiting such use in clinical practice." (PMID 38544832, 2024). "BRCA1 and BRCA2 stand out as widely recognized genetic susceptibility genes for ovarian cancer." (PMID 38461424, 2024). "For example, even though heterozygous loss of BRCA1 greatly increases risk of breast and ovarian cancer, BRCA1 is under strong rather than extreme selection." (PMID 37292653, 2024). "In conclusion, it is crucial to continue exploring genetic risk factors for breast and ovarian cancers in individuals who do not have BRCA1 and BRCA2 mutations." (PMID 38660159, 2024). "The second group included wild-type BRCA1 and BRCA2 controls (healthy individuals with benign gynecological diseases) and women with BRCA1 mutations but no ovarian cancer." (PMID 38877504, 2024). "Similarly, in ovarian cancer, BRCA1 epimutations are infrequently recorded in low-grade serous as well as nonserous tumors as compared to more frequent observations in HGSOC." (PMID 40225940, 2024). "Since more recent studies showed that this percentage is up to 90% in BRCA1/2-PV carriers, the effect of RRS on ovarian cancer risk reduction might even be higher." (PMID 38907139, 2024). "The intraperitoneal delivery of the retroviral LXSN‐BRCA1 vector in BRCA‐1‐deficient ovarian cancer did not result in any clinical responses, possibly because of the vector's instability in the body." (PMID 38827026, 2024). "An increased risk of breast and ovarian cancer due to HRT in BRCA1/2-pV carriers without RRSO cannot be excluded based on current data." (PMID 39259360, 2024). "While BRCA1 is well-known for its role in hereditary breast and ovarian cancer, there’s emerging evidence that it may also play a role in neuronal health, particularly in DNA repair mechanisms." (PMID 39264583, 2024). "Furthermore, the involvement of the homologous recombination DNA repair pathway, which is frequently affected by BRCA1 and BRCA2 mutations, further underscores the link between these genetic alterations and the development of ovarian cancer." (PMID 38543119, 2024). "Our study differs from the research conducted by Manchanda et al31 on the cost-effectiveness of population-based testing for BRCA1, BRCA2, RAD51C (OMIM 602774), RAD51D (OMIM 602954), BRIP1 (OMIM 605882), and PALB2 mutations for preventing breast and ovarian cancer in the following ways." (PMID 38353949, 2024). "The combinatorial modality resulted in synergistic effects in HRDhigh sarcoma cells as well as in BRCA1-mutated ovarian cancer cells but not in HRDlow sarcoma cells." (PMID 39535612, 2024). "Clinically, BRCA1- and BRCA2-mutated ovarian cancers have been treated as the same disease." (PMID 38017453, 2023).